MAPT (microtubule associated protein tau)
Diseases named in the same sentence as MAPT in open-access papers (continued):
Sharing a sentence is not in itself a finding about the gene and the disease.
tauopathies (continued). "However, the failure of developing NFTs in APPNLGF x MAPT dKI mice highlights the challenges of naturally modeling tauopathy that aligns with clinical AD development chronologically, when tauopathy develops decades after amyloidosis." (PMID 38462606, 2024). "Since Tg12099(+/−) rats do not exhibit spontaneous tauopathy, we surmised that the expression of MAPT*P301S rendered neurons susceptible to the uptake and propagation of tau prions." (PMID 39160375, 2024). "This consideration gains even more relevance assuming that each Ub configuration may have a specific role in disease pathogenesis and may represent a potential neoepitope, as documented for Ub-tau (MAPT gene) species in tauopathies." (PMID 39337505, 2024). "The three major genes implicated in genetic FTLD are microtubule-associated protein tau (MAPT), progranulin (GRN) and chromosome 9 open reading frame 72 (C9orf72), where MAPT mutations are associated with a primary tauopathy and GRN and C9orf72 are associated with TDP-43 pathology." (PMID 38147792, 2024). "There are over 50 mutants of the MAPT gene that have been identified in several tauopathies." (PMID 38552740, 2024). "The MAPT H1 haplotype, for example, has been found to be associated with increased risk in developing PSP, CBD, and AD (only in non-ApoE-4 carriers), suggesting a common genetic link between tauopathies that contain 4-repeat scripts." (PMID 36597124, 2023). "Although MAPT mutations are not a cause of AD, they are causal in other tauopathies including frontotemporal dementia (FTD) and Pick’s disease." (PMID 37950311, 2023). "Missplicing of MAPT leads to tauopathy, with tau aggregation and neurofibrillary tangles." (PMID 37707954, 2023). "Although MAPT KI mice do not spontaneously develop tau-associated pathology, they are still a useful model to investigate mechanisms of tauopathy." (PMID 37842124, 2023). "To determine whether downregulation in peripheral leukocytes was mirrored by changes in brain myeloid cells in the context of tauopathy, we analyzed a publicly available brain RNA-seq dataset derived from MAPT P301S mouse hippocampal microglia." (PMID 37464408, 2023). "This is crucial as most tauopathies are sporadic and not downstream of missense mutations in the microtubule associated protein tau (MAPT) locus." (PMID 38161790, 2023). "Taken together, the lack of tau pathology and the expression of both 3R and 4R tau isoforms makes MAPT KI mice ideal models for future studies aiming to define the precise consequences of tauopathy induced by the injection of pathological tau seeds or upstream pathology-initiating factors." (PMID 37842124, 2023). "Increased levels of CSF p-tau217 have also been found in non-AD tauopathy carriers of the MAPT mutation R406W." (PMID 36927491, 2023). "Moreover, miR-132-3p, which is frequently downregulated in AD and other tauopathies, directly targets MAPT mRNA to inhibit its expression, and its deletion in AD model mice leads to tau aggregation." (PMID 38003448, 2023). "Our findings may also be relevant to the emerging role of hyperexcitability in tauopathies, an effect that has also been observed in MAPT V337M mutant iPSC-derived neurons." (PMID 35985329, 2022). "In this study we found that local correction of abnormal exon 10 alternative splicing of the MAPT transcript could achieve a significant recovery of cognitive and motor impairments in a model of tauopathy." (PMID 36277399, 2022). "In summary, results presented in this study are a proof of concept that local regulation of abnormal MAPT splicing could be an effective approach to stop the progression of tauopathy." (PMID 36277399, 2022). "SMaRT can efficiently modulate MAPT alternative splicing in human-derived neurones and can significantly reduce neurodegenerative pathology and improve cognitive impairment in-vivo in a mouse model of tauopathy." (PMID 35067193, 2022).
tauopathies (continued). "While not every tauopathy has associated causative MAPT mutations, it has been consistently found that tau pathology is strongly correlated with the degree of cognitive decline, solidifying its importance in the disease progression." (PMID 35592115, 2022). "Others have chosen to group MAPT variants based on morphological classes of sporadic tauopathies (i.e. PiD, CBD, GGT, PSP), arguing that it provides a direct means to compare genetic and sporadic tauopathies." (PMID 36066634, 2022). "Macrophage activation in the injured hTau mouse model of tauopathy raises the question whether there is a relationship between MAPT pathology and alterations in macrophage activation following TBI." (PMID 36389767, 2022). "While in secondary tauopathies, including AD, myotonic dystrophy, Down syndrome, etc., no pathogenic MAPT mutation has been found." (PMID 35392986, 2022). "Globular glial tauopathy (GGT) is a rare non-familial 4R tauopathy; only a few individual cases have been linked to MAPT mutations." (PMID 34425874, 2021). "To address this knowledge gap, we explored the relationship between adolescent concussion, neuroinflammation, and tauopathy using adolescent P301S transgenic mice that harbor a mutant form of the human microtubule-associated protein tau (MAPT) and exhibit similar tau pathology to human tauopathies." (PMID 33477535, 2021). "Furthermore, we compared CTE to other tauopathies, including frontotemporal lobar degeneration due to MAPT mutations (FTLD-MAPT), progressive supranuclear palsy (PSP), and corticobasal degeneration (CBD)." (PMID 34172091, 2021). "Surprisingly, genome-wide association studies identified the MAPT haplotype also as major risk factor for Parkinson’s disease (PD), which is not considered a tauopathy but a synucleinopathy." (PMID 34532319, 2021). "Majority of tauopathies are sporadic, but for example FTDP-17 is strictly inherited and all the different clinical and neuropathological subtypes of FTDP-17 are caused by different mutations in the MAPT gene." (PMID 31667556, 2020). "A MAPT variant, p.A152T, has also been found as a risk factor for PSP and other tauopathies." (PMID 31695675, 2019). "While mutations in the tau gene (MAPT) are known to cause primary tauopathies, no MAPT mutations were linked to AD until the discovery of the A152T mutation, which acts as a risk factor for AD." (PMID 30674342, 2019). "Also in the brains of patients with primary tauopathies, including Pick’s disease, progressive supranuclear palsy (PSP) and frontotemporal dementia (FTD) caused by MAPT mutations, the GVB abundance is significantly higher than in elderly controls." (PMID 31456031, 2019). "Therefore, human MAPT sequences are required to model human tauopathies and so almost all mouse models of tau deposition are transgenic animals expressing the human gene." (PMID 31203387, 2019). "However, the iPSC model of MAPT p.R406W is uninformative with regards to PSEN1 mutations in AD or FTLD-TDP, further supporting its specificity for primary tauopathy." (PMID 30546007, 2018). "Both MAPT IVS10+16 and IVS10+16/P301S iPSCs, in conjunction with their parental isogenic wild-type cells, are useful tools to further elucidate the role of the IVS10+16 mutation, the P301S mutation, and the mechanisms underlying FTDP-17 and other tauopathies." (PMID 30057263, 2018). "Here, we performed whole genome gene expression in a genomic mouse model of tauopathy that expressed human MAPT gene under the control of endogenous human MAPT promoter and also were complete knockout for endogenous mouse tau [referred to as ‘hTauMaptKO(Duke)′ mice]." (PMID 28367114, 2017). "First, the presence of mutations in the genes encoding presenilin 1 (PS1), amyloid precursor protein (APP), and tau (MAPT) have been identified as causing familial AD (PS1M146V, APPSWE) or tauopathies including frontotemporal dementia and parkinsonism linked to chromosome 17 (MAPTP301L)." (PMID 28774322, 2017).
tauopathies (continued). "The ability to assay the effect of genetic variation at the expression level is the first step in studying a range of tauopathies, from diseases caused by specific tau mutations such as those found in FTDP-17, to diseases with strong genetic associations with MAPT as in PD, PSP, and CBD." (PMID 28689993, 2017). "Overall, the analyses suggest USP9 may contribute to molecular gender differences observed in tauopathies and provide a new target for intervention strategies to modulate MAPT expression." (PMID 27878758, 2017). "In further support of this idea, mice that expresses human oligomeric Aβ and human τ eventually develop NFT pathology even in the absence of tauopathy-associated mutations in the MAPT gene." (PMID 28401333, 2017). "One hereditary tauopathy is FTDP-17, which is caused by mutations in MAPT." (PMID 28082867, 2016). "Activated microglia spatially coexist with microtubule-associated protein tau (Mapt or tau)-burdened neurons in the brains of human AD and non-AD tauopathies." (PMID 26089772, 2015). "As such, the splicing pattern of MAPT transcripts could be determinant in tauopathy-type neurodegenerative processes." (PMID 26170022, 2015). "Mutations in MAPT cause FTD and PSP, and hyperphosphorylated tau accumulation is a hallmark in a number of neurodegenerative conditions, including AD, PSP, FTD and others, collectively named ‘tauopathies’." (PMID 24603599, 2014). "TDP-43 pathology has been identified in a subset of different proteinopathies including tauopathies that occur in the absence of MAPT mutations." (PMID 23666556, 2013). "The identification of MAPT as a genetic risk factor for PD was surprising, given that PD is not a tauopathy." (PMID 23938306, 2013). "However, unlike aberrant copy numbers of APP and SNCA, which have been clearly identified in hereditary AD and PD pedigrees, respectively, evidence for a relationship between MAPT gene dosage and either PD or tauopathies remains primarily circumstantial." (PMID 23494099, 2013). "Although the alternative splicing of MAPT exon 10 in healthy and diseased brains has been well characterized, until recently no studies had examined the regulation of exons 2 and 3, and thus the contribution of N‐terminal tau isoforms to primary tauopathies was unexplored." (PMID 38170841, 2024). "Thus, the tauopathy phenotypes described here arose from the MAPT*P301S transgene." (PMID 39160375, 2024). "On the other hand, mutations in MAPT gene lead to tauopathies, but not to AD." (PMID 37895336, 2023). "Importantly, motor impairments do not interfere with important behavioral paradigms, such as the MWM, which is the case in various other tauopathy mouse models with a more aggressive motor phenotype, like for example, the widely used PS19 tauopathy model also harboring the P301S MAPT mutation." (PMID 37895469, 2023). "Mutations in microtubule-associated protein tau (MAPT) may encode the tau protein associated with frontotemporal dementia and alter its ability to interact and bind with microtubules, leading to a tauopathy process." (PMID 36834835, 2023). "Also, in the human brain GVBs are observed in different tauopathies independent of the tau isoform in the inclusions or the presence of a MAPT mutation." (PMID 36517915, 2022). "The microtubule-associated protein tau (MAPT) plays an essential role in numerous neurodegenerative diseases, and pathogenic species of tau form neurotoxic aggregates, which correlate with cognitive deficits and neurodegeneration in humans and animal models of tauopathy." (PMID 34862271, 2022). "Additionally, the discovery of microtubule-associated protein tau (MAPT) gene mutations and the strongest genetic risk factor of tauopathies—an increase in the presence of the ε2 allele of apolipoprotein E (ApoE)—provide important clues to understanding tau pathology progression." (PMID 33672982, 2021).
tauopathies (continued). "Intriguingly a subset of tauopathies, including corticobasal degeneration (CBD), progressive supranuclear palsy (PSP), fronto-temporal lobar degeneration with tau mutations (FTLD-tau) and myotonic dystrophy, are thought to be driven by changes in MAPT pre-mRNA alterative splicing." (PMID 29634760, 2018). "In our study, after excluding H1/H1 subjects, the presence of APOE ε2/ε2 genotype further increased the risk of PSP and CBD, suggesting that the association of APOE ε2/ε2 and tauopathy may be independent of MAPT H1 haplotype." (PMID 30348994, 2018). "Discovering the precise sets of MAPT functional variants; and assessing their biologic consequence, especially on transcriptional regulation, may be critical to deciphering the commonalities and distinctions in the etiology of LOAD vs. primary tauopathies." (PMID 25324900, 2014). "The results confirm that the region surrounding MAPT is associated with idiopathic PD in our neuropathologically proven PD cohort and, therefore, that this association does not result from contamination with primary tauopathies, such as PSP." (PMID 22221882, 2012). "While to this day no mutations have been found in the tau-encoding MAPT gene in AD patients, molecular analysis of another tauopathy, frontotemporal dementia with parkinsonism linked to chromosome 17 (FTDP-17), has revealed characteristic mutations in this gene." (PMID 20721342, 2010). "Moreover, given the population‐level differences in MAPT haplotypes, this resource offers a unique opportunity to examine whether ancestry‐specific genetic variations modify tau expression, splicing, or aggregation in tauopathies." (PMID 40219788, 2025). "TAU is a natural therapeutic target for MAPT-related FTD, and an attractive target for related tauopathies such as AD, as there is a strong correlation between the amount of NFTs and cognitive decline, and Mapt-KO mice are healthy." (PMID 38554150, 2024). "However, to investigate human tauopathies that are not caused by MAPT overexpression, and to avoid experimental artifacts, it is important to characterize HCN channel–associated synaptic changes in a transgenic mouse model in which total tau is expressed at an endogenous level, such as Tau35 mice." (PMID 38994745, 2024). "Instead, overexpression of mutant MAPT genes results in robust NFT deposition in rodent brains, which led to the wide adaptation of the mutant models to study tauopathy." (PMID 37955806, 2024). "In rodent brains, neuronal overexpression of mutant MAPT is sufficient for the development of NFT pathology and the onset of neurodegeneration, leading to the successful construction of numerous tauopathy disease models." (PMID 37955806, 2024). "Patients with tauopathies such as PSP and CBD exhibited higher expression of these MAPT isoforms compared to those with other neurodegenerative conditions, indicating a stronger involvement of tau pathology in these diseases." (PMID 39766775, 2024). "Previously we showed that interaction of MAPT with HNRNPA2B1 and m6A RNA mediates the progression of tauopathy." (PMID 37292629, 2023). "Therefore, in this study, we have analyzed and compared the PTMs in the pathological tau proteins prepared from a wide range of tauopathies (AD, PSP, CBD, GGT, PiD, and FTDP-17T with MAPT intron 10 mutation) in order to establish whether the PTMs show disease-specificity." (PMID 33250706, 2020). "The expression of GABA receptor genes, including GABRB2 and GABRG2, were consistently reduced in iPSC-derived neurons and brains from MAPT p.R406W carriers, PSP brains, and mouse models of tauopathy." (PMID 30546007, 2018). "We conclude that the set of gene-edited iPSC lines with MAPT IVS10+16 and MAPT IVS10+16/P301S mutations that we described could serve as a platform to identify new targets for drug development and to reveal the mechanisms underlying FTDP-17 and other tauopathies." (PMID 30057263, 2018).
tauopathies (continued). "However, not all of the known mutations in MAPT result in altered tau splicing and furthermore, the molecular mechanisms that link these mutations to the observed pathological and clinical features of the tauopathies are not well understood." (PMID 26459111, 2016). "The possible contribution of internal MAPT transcripts such as saitohin (STH) to MAPT regulation or function makes it of special interest in relation to tauopathies, other dementias and, more recently, schizophrenia." (PMID 27030133, 2016). "Due to these negative results, another phase 1b placebo-controlled “basket” trial (NCT03658135) targeting four primary tauopathies—CBD, FTLD with MAPT mutations, CTE, and non-fluent PPA—was discontinued." (PMID 40588759, 2025). "Using Tg12099(+/−) rats, which do not display overt signs of tauopathy yet express the MAPT*P301S transgene, we unilaterally injected tau fibrils (1 mg/mL) or PBS (vehicle) into the hippocampus and overlying cortex of 2-month-old Tg12099(+/−) rats." (PMID 39160375, 2024). "The genetic profiles of some tauopathies, i.e. FTD, PSP, CBD, PD, might show differences across ethnic groups, since the MAPT gene has two haplotypes (H1 and H2)." (PMID 38554150, 2024). "The non-inflammatory tauopathy neuropathological signature and overrepresentation of MAPT H1/H1 genotype as seen in other sporadic tauopathies is consistent with a primary neurodegenerative process." (PMID 39063198, 2024). "While pathogenic mutations in the tau gene (MAPT) have been linked to FTD and other primary tauopathies, no pathogenic MAPT mutations have been associated with AD." (PMID 37016391, 2023). "To attempt to correlate the phenotypes of RELN-COLBOS in mice and humans, we used a crossbreeding strategy, using our knockin mouse model and a tauopathy mouse model, specifically the STOCK Tg(Prnp-MAPT*P301L)JNPL3Hlmc mouse from the Hutton’s laboratory, distributed by Taconic Biosciences." (PMID 37188781, 2023). "Thus, genetic variations in both MAPT and LRRC37A2 appear to be important determinants of tauopathies and neurodegenerative disorders." (PMID 35396452, 2022). "Although familial mutations in the MAPT gene have not been identified in FAD patients, the identification of familial FTD-linked mutations has facilitated the development of tauopathy mouse models." (PMID 35799899, 2022). "Similarly, it has recently emerged that limited MAPT mutations are permissive to seeding in a cell-based assay, it would be interesting to identify whether this is also the case in a more intact system and whether a seeded BSC model of tauopathy can be developed." (PMID 31791377, 2019). "18F-AV1451 PET studies have also demonstrated a distinct pattern of tracer binding in non-AD tauopathies such as PSP, CBD, and microtubule associated tau (MAPT) mutation carriers." (PMID 30186106, 2018). "Although PD is not typically regarded as a tauopathy and is instead characterized by alpha-synuclein pathology, a link between MAPT and PD is now well established." (PMID 25577413, 2015). "This corroborates what has been observed in humans (see Co-occurrence of tauopathies and synucleinopathies and SNCA and MAPT in genetic studies sections) and reinforces the idea that the interplay between αsyn and tau are pivotal in the neurodegenerative process." (PMID 25352339, 2014). "Our data does not support the positive association of htSNPs forming the H1c haplotype within MAPT with LOAD and suggests that rs242557 is unlikely to be the functional allele as previously suggested in some positive associations reported for tauopathies." (PMID 17266761, 2007). "Rescuing SNHG8 expression leads to reduced stress granule formation and reduced TIA1 levels in immortalized cells and in MAPT mutant neurons, suggesting that dysregulation of this non-coding RNA is a causal factor driving stress granule formation via TIA1 in tauopathies." (PMID 37730840, 2023).